MTOR (mechanistic target of rapamycin kinase)
Diseases named in the same sentence as MTOR in open-access papers (continued):
Sharing a sentence is not in itself a finding about the gene and the disease.
bladder cancer (continued). "For example, puerarin inhibits cell proliferation of bladder cancer via the mTOR/p70S6K signaling pathway." (PMID 32111101, 2020). "For example, PTE treatment significantly increases autophagy-associated protein LC3-II and Bcl-xl (negative regulator of apoptosis) levels through AKT/mTOR/p70S6K axis regulation in T24 human bladder cancer cells." (PMID 32375296, 2020). "PTEN has a potential impact on response to mTOR inhibitors via the PI3K/Akt/mTOR pathway in the therapy of bladder cancer." (PMID 33344221, 2020). "Pirarubicin induced an autophagic cytoprotective response via inhibition of mTOR/p70S6K signal route in human bladder carcinoma." (PMID 33194716, 2020). "A recent study has investigated the effect of AZD2014 and BEZ235 in invasion in comparison with single AKT or mTOR inhibitors in bladder cancer cells." (PMID 33659215, 2020). "In up to 40% of bladder cancers, mTOR pathway activation is closely involved with tumor progression." (PMID 32512849, 2020). "We demonstrated that combination therapy with an AKT inhibitor (AZD5363) and an mTOR inhibitor (AZD2014 or BEZ235) exerted a synergistic effect on the viability and colony formation ability of bladder cancer cells carrying PI3KCA and mTOR mutations." (PMID 32325639, 2020). "Since over 40% of bladder cancers exhibit constitutive activation of the phosphatidylinositol 3-kinase/protein kinase B/mechanistic target of rapamycin (PI3K/AKT/mTOR) pathway, suppressing activation is a treatment option." (PMID 31167517, 2019). "In bladder cancer, the PI3K-AKT-mTOR pathway was associated with sialyl-Tn antigen, whereby inhibition of mTOR led to reduced expression of this sialyl-Tn antigen." (PMID 30761272, 2019). "A subset of bladder cancer patients, refractory to first line platinum-based chemotherapy, has been reported to benefit from the mTOR-inhibitor, temsirolimus." (PMID 31167517, 2019). "mTOR pathway activation has been shown to be closely involved in bladder cancer tumorigenesis and to be a predictor of disease progression and poor cancer specific survival." (PMID 31167517, 2019). "This is important because confirmation of “oncogene addiction” (reviewed in14,15) to mutant HRAS or interrelated components of the FGFR3 or PI3K/AKT/mTOR pathways would allow development of targeted approaches to treat noninvasive bladder cancer." (PMID 30670749, 2019). "In good corroboration, whole-exome and targeted sequencing in patients with aggressive bladder cancer has identified mTOR as an important target in treating patients with metastases." (PMID 31167517, 2019). "Metformin has been shown to suppress bladder cancer cell proliferation and potentiate cancer cell apoptosis via the mechanistic target of rapamycin (mTOR) pathway." (PMID 30729133, 2019). "Prior the immunotherapy era, potential options in the therapeutic armamentarium included kinase inhibitors targeting the PI3K/AKT/mTOR pathway that was known to be activated in bladder cancer." (PMID 29454321, 2018). "The extract has also been shown to inhibit the mTOR pathway and induce autophagy in bladder cancer cell lines." (PMID 29984244, 2018). "It has also been shown to inhibit the mTOR pathway and induce autophagy in bladder cancer cell lines." (PMID 29984244, 2018). "Although mTOR inhibitors have not been applied as the first‐line treatment for treating invasive or metastatic urinary bladder cancer, inhibition on mTOR and its downstream signal has been applied in vitro and in clinical trials." (PMID 30117312, 2018). "In bladder cancers, p-mTOR staining was positive in a subset of invasive UC and intense in the superficial layer of papillary UC, which is in concordant with earlier data." (PMID 28831205, 2017).
bladder cancer (continued). "The expression of phospho-S6 (a marker of mTOR activity) was found in 55% of muscle-invasive bladder cancers with evident lymph node metastases." (PMID 29214525, 2017). "Based on a bladder cancer cell model, expression of p27 seems to be directly mediated through an mTOR-dependent mechanism, presumably via mTORC1." (PMID 29299126, 2017). "Further investigations should evaluate the effect of concomitant HDAC and mTOR inhibition in bladder cancer cells." (PMID 29299126, 2017). "A previous study has reported that the PI3K/Akt/mTOR pathway plays a crucial role in cancer progression and thus this signaling pathway becomes a therapeutic target for bladder cancer." (PMID 28746469, 2017). "In conclusion, TNTs promoted spontaneous intercellular mitochondria trafficking followed by increased Akt activation, mTOR signaling, and invasiveness of bladder cancer cells." (PMID 28107184, 2017). "In mouse endometrial and bladder cancers, loss of PTEN and LKB1 leads to activation of the AKT/mTOR pathway and results in tumors sensitivity to PI3K and mTOR inhibition." (PMID 29228674, 2017). "Blocking the activation of Akt with LY294002 or mTOR with rapamycin significantly prevented miR‐222‐induced proliferation and restored the sensitivity of bladder cancer cells to cisplatin." (PMID 26800397, 2016). "In the present study, we found ATR-1 exhibited dose-dependent anti-tumor effects on human bladder cancer cells such as causing cell cycle arrest, inducing apoptosis and inhibition of PI3K/Akt/mTOR signaling pathway." (PMID 26931119, 2016). "miR‐222 activated the Akt/mTOR pathway and inhibited cisplatin‐induced autophagy in bladder cancer cells by directly targeting protein phosphatase 2A subunit B (PPP2R2A)." (PMID 26800397, 2016). "Activation of PI3K/Akt/mTOR also contribute to the migration, invasion and chemoresistance of bladder cancer." (PMID 26931119, 2016). "It is well documented that constitutive activation of PI3K-Akt-mTOR signaling pathway, which contributes to the development of bladder cancer, can also lead to the down-regulation of Bad." (PMID 26931119, 2016). "Recent evidence indicates that AKT is frequently activated in many types of human cancer, and activated PI3K/AKT/mTOR signaling pathway is a significant contributor to tumor progression and poor prognosis, including bladder cancer." (PMID 26733306, 2016). "Recent high throughput genomic studies have revealed several gene and pathway alterations associated with MIBC, including PI3K/AKT/mTOR and ERK/MEK/RAS pathways as drivers of bladder cancer progression and potential targets for therapeutic interventions." (PMID 27823983, 2016). "Accordingly, mTOR-inhibitors have been extensively explored in pre-clinical settings and two phase I/II clinical trials for bladder cancer are ongoing." (PMID 26569621, 2015). "The expression of mTOR and mTOR pathway members, such as Phos-S6, have been reported in bladder carcinoma." (PMID 25523514, 2015). "In this study, we explored the antitumor effect of NVP-BEZ235, a dual PI3K/mTOR inhibitor in cisplatin-resistant human bladder cancer cells and its synergistic interaction with cisplatin." (PMID 24969552, 2014). "The Cancer Genome Atlas project has identified the AKT/mTOR pathway as a critical therapeutic target in bladder cancer." (PMID 25136960, 2014). "Deregulation of the mTOR pathway has been related to oncogenesis in several malignancies, including bladder cancer." (PMID 25493074, 2014). "In conclusion, we herein demonstrate for the first time that evodiamine induces apoptosis and enhances TRAIL-induced apoptosis in human bladder cancer cells, possibly through mTOR/S6K1-mediated downregulation of Mcl-1." (PMID 24566141, 2014).
bladder cancer (continued). "Based on these ideas, a few studies have assessed and demonstrated the antitumor effect of mTOR inhibitors for bladder cancers in pre-clinical or clinical settings." (PMID 24969552, 2014). "Deregulation of the PI3K/AKT/mTOR pathway generates a favourable oncogenic environment and has been documented in a variety of human tumours including bladder cancer." (PMID 23799002, 2013). "Our study also demonstrated that mTOR signaling pathway was inhibited by metformin in bladder cancer cells, as evidenced by the decreased phosphorylation of mTOR, S6K1, and 4E-BP1." (PMID 24351837, 2013). "Collectively, these results suggest that metformin treatment leads to activation of AMPK and inhibition of the mTOR signaling pathway in bladder cancer cells." (PMID 24351837, 2013). "The phosphoinositide-3 kinase-AKT-mammalian target of rapamycin (mTOR) pathway has been identified as a candidate pathway in bladder cancer progression in several recent clinicopathological studies." (PMID 24312263, 2013). "Altering cell cycle by inhibiting the mTOR signaling pathway in combination with radiation have favorable outcomes and is a promising therapeutic modality for bladder cancer." (PMID 23799002, 2013). "We recently published the first report demonstrating significant antitumor activity via inhibiting mTOR with RAD001 in bladder cancer models in vitro and in vivo." (PMID 23799002, 2013). "The PI3K, AKT and mTOR signal transduction pathways regulate cell survival, proliferation and invasion, all key functions in the progression of bladder cancer." (PMID 23599794, 2013). "AKT/PI3K/mTOR pathway alterations are very frequent in bladder cancer, with 73% of human bladder tumours characterised by alterations in one of the major pathway components: TSC1, PI3K (PIK3CA) or PTEN." (PMID 21283818, 2011). "The AKT/PI3K/mTOR pathway is frequently altered in a range of human tumours, including bladder cancer." (PMID 21283818, 2011). "In vitro and in vivo models of bladder cancer have established the importance of the mTOR pathway in controlling cancer progression and metastasis." (PMID 19128503, 2009). "Now we intend to verify the efficacy of sirolimous mTOR inhibition, in other bladder cancer cell lines (5637, HT1376 and MC)." (PMID 19128503, 2009). "The findings of the present study revealed that sirolimus inhibits T24 bladder cancer cell proliferation and decrease the cell viability including in clinical dose of this mTOR inhibitor." (PMID 19128503, 2009). "Alterations in the pathway regulating mTOR occur in many solid malignancies including bladder cancer." (PMID 19128503, 2009). "The IGF2BP3-ST3GAL6-PI3K/AKT/mTOR signaling axis may contribute to this process and may serve as a potential biomarker and therapeutic target in bladder cancer." (PMID 42279297, 2026). "Moreover, amiodarone inhibited the mTOR and p44/p42 signaling pathways, which are molecular targets with high relevance in bladder cancer and can partially explain the observed phenotype." (PMID 40353763, 2025). "Gαi3 interacts with receptor tyrosine kinases such as the epidermal growth factor receptor (EGFR) and FGFR, mediating the activation of the downstream PI3K/AKT/mTOR signaling cascade to promote the proliferation, migration, and invasion of bladder cancer cells." (PMID 41438986, 2025). "Similarly, STIL has been reported to decrease c-Myc expression via the PI3K/AKT/mTOR pathway, thereby inhibiting bladder cancer cell proliferation." (PMID 40961099, 2025). "Dysregulation of PI3K-Akt-mTOR signaling was found in 40% of bladder cancers." (PMID 40183046, 2025). "Our most promising candidate, amiodarone, reduced bladder cancer growth in vitro and in vivo, an effect that might be mediated by the inhibition of mTOR, with possible implications also for the ERK1/2 pathway." (PMID 40353763, 2025).
bladder cancer (continued). "In another study, N‐butyl‐N‐(4‐hydroxybutyl) nitrosamine was used to induce bladder cancer and it was noted that luteolin is markedly lowered the tumor dimension, inhibited cell proliferation and mTOR signaling, lowered the Ki67‐labeling index and p‐S6 expressions." (PMID 39830909, 2025). "To further confirm whether DUSP6 mediates mitophagy in bladder cancer through the mTOR pathway, we pre-treated DUSP6 knockdown cells with medium containing 1.5 μM of mTOR agonist MHY1485 for 12 hours, and observed that the level of mitophagy was decreased." (PMID 40936711, 2025). "There results indicate that the DUSP6 mediates mitophagy through mTOR pathway in bladder cancer." (PMID 40936711, 2025). "In addition, OTUD5 knockdown also enhances the sensitivity of bladder cancer cells to everolimus, an inhibitor of mTOR." (PMID 41050073, 2025). "Our results showed that amiodarone inhibited the mTOR pathway in bladder cancer cell lines." (PMID 40353763, 2025). "Notably, our analysis showed that patients with bladder cancer exhibiting high FADS2 expression were more sensitive to the mTOR inhibitor rapamycin." (PMID 40682485, 2025). "Therefore, HSPB6 serves a critical function not only in regulating EMT but also in suppressing the PI3K/AKT/mTOR signaling pathway, further underscores its potential as a therapeutic target in the treatment of bladder cancer." (PMID 39608715, 2024). "Melatonin also represses the PI3K/AKT/mTOR signaling in bladder cancer." (PMID 38473317, 2024). "The study concluded that the combination of nelfinavir and ritonavir effectively kills bladder cancer cells through multiple mechanisms, including ER stress induction, mTOR pathway inhibition, and histone acetylation, making it a promising therapeutic strategy for bladder cancer." (PMID 39451754, 2024). "For example, a combination of carbonic anhydrase inhibitor, acetazolamide (AZ), and SFN is suggested to potentially suppress cell proliferation and enhanced apoptosis in HTB-9 and RT112(H) bladder cancer cell lines by suppressing Akt signaling proteins such as p-Akt, p-mTOR and p-S6." (PMID 38254735, 2024). "This suggests that reducing ATP levels might be the primary mechanism behind the inhibition of Akt-mTOR cascade in bladder cancer cells induced by MB-10." (PMID 38467612, 2024). "For example, in bladder cancer, lncRNAs such as TUG1 and SNHG1 have been implicated in modulating autophagy and contributing to therapy resistance through interactions with key signaling pathways like PI3K/Akt/mTOR and PP2A catalytic subunit, respectively." (PMID 39512820, 2024). "The mechanisms underpinning the oncogenic mode of action of MIR4435-2HG in bladder cancer cells may involve the phosphorylation of mTOR signaling molecules, in which MIR4435-2HG may act as a scaffold for the recruitment of activators." (PMID 37355516, 2023). "Similarly, sodium butyrate activated autophagy via the AMPK/mTOR pathway and ROS-mediated apoptosis and inhibited migration by the miR-139-5p/Bmi-1 signaling pathway in bladder cancer cells." (PMID 36593951, 2023). "Cell cycle, histone pathway, PI3K/AKT/mTOR, and chromatin remodeling are the four major signaling pathways identified to be deregulated in bladder cancer according to TCGA-derived data, with cell-cycle-related gene alterations the most common, present in over 90% of bladder carcinoma cases." (PMID 37046810, 2023). "Furthermore, it affects the advancement of bladder cancer by regulating cell cycle factors and the signaling of mammalian target of rapamycin (mTOR)." (PMID 37998733, 2023). "In addition, the knockdown of DUXAP10 also inhibited the PI3K/Akt/mTOR signaling pathway in bladder cancer cells." (PMID 37627900, 2023). "In addition, the increase of DTL indicated a poor prognosis in malignant manners of bladder cancer through the mTOR/Akt signaling cascades." (PMID 36741311, 2023).
bladder cancer (continued). "Interestingly, when RAC3 was knocked down, the growth and migration of bladder cancer cells were inhibited through the PI3K/AKT/mTOR pathway-mediated autophagy induction." (PMID 37056933, 2023). "In addition to protein and gene expression, hAM homogenate also decreased Akt and mTOR phosphorylation levels in muscle-invasive bladder cancer T24 cells." (PMID 37932474, 2023). "Our findings showed that PEPE2 incubation could decrease the TCTP amount in bladder cancer, thus matching the findings that TCTP serves as an anti-apoptotic protein and is linked to the mTOR pathway and cell cycle regulation." (PMID 36362994, 2022). "In bladder cancer treatment, TET induced autophagy in human bladder cancer cells by regulating AMPK/mTOR signaling, which favors apoptosis induction, suggesting that it may be a potential anticancer candidate for the treatment of bladder cancer." (PMID 35684449, 2022). "Using network pharmacology, we found that gypenosides may affect PI3K/AKT/mTOR signaling, which is a crucial regulator of bladder cancer cell growth and survival." (PMID 35402614, 2022). "IHS analysis showed that mTOR was upregulated in prostate and bladder cancer." (PMID 35082928, 2022). "Next, we assessed whether gypenosides act as tumor suppressors of bladder cancer by repressing PI3K/AKT/mTOR signaling, as predicted by network pharmacology." (PMID 35402614, 2022). "Therefore, although PIK3CA is a valuable therapeutic target for inhibitors of PI3K/AKT/mTOR pathways in advanced bladder cancer, the detailed expression status of the mutations should be carefully evaluated when the targeted therapy is considered." (PMID 35846154, 2022). "In addition, studies have shown that knockdown of UBE2S promotes apoptosis, inhibits cell proliferation, and inhibits the mTOR signaling pathway in vitro and in vivo, thereby ultimately inhibiting the tumor progression of bladder cancer." (PMID 35658829, 2022). "The combination of olaparib and metformin can jointly inhibit the PI3K/Akt/mTOR signaling pathway and exert a synergistic antitumor effect, which provides an experimental basis for the combination of metformin and olaparib in the treatment of bladder cancer." (PMID 35783012, 2022). "Additionally, betulinic acid induced autophagy and apoptosis in bladder cancer cells through the Bmi-1/ROS/AMPK/mTOR/ULK1 axis." (PMID 35897796, 2022). "Further, given the genetic complexity of bladder cancer, other pathways associated with the PI3K/AKT/mTOR pathway may also play a role in the antibladder cancer effect of gypenosides." (PMID 35402614, 2022). "Here, we demonstrated that gypenosides may inhibit bladder cancer cell proliferation by inhibiting the PI3K/AKT/mTOR pathway." (PMID 35402614, 2022). "This review also explores current preclinical studies and clinical trials targeting the mTOR pathway, and concludes with future directions of research that could more robustly define and target aberrant mTOR activity in bladder cancer." (PMID 35326708, 2022). "Finally, bladder cancers with knockdown or overexpression of UCHL5 were treated with either SC79 or LY294002 to examine the participation of the AKT/mTOR signaling pathway and the expression of downstream targets c-Myc, SLC25A19, and ICAM5." (PMID 36428630, 2022). "Moreover, its underlying mechanism was further explored in bladder cancer cells, especially the role of PI3K/AKT/mTOR." (PMID 35246010, 2022). "Another recent study using seven human bladder cancer cell lines in a 3D high-throughput screening platform showed that the combination of AKT inhibitor (AZD5363) with a dual PI3K/mTOR inhibitor (NVP-BEZ235) or an mTOR inhibitor exhibited synergistic effects on cell viability and colony formation." (PMID 35326708, 2022). "New discoveries regarding signaling convergence onto mTOR complexes in bladder cancer could yield unique insights the biology and targeting of this aggressive disease." (PMID 35326708, 2022).